DISC1FP1 (DISC1 fusion partner 1)
Synonyms: Boymaw
Gene: Long non-coding RNA gene on chromosome 11 (90,251,204 to 90,915,649, forward strand). Ensembl gene ENSG00000261645.
Diseases named in the same sentence as DISC1FP1 in open-access papers:
DISC1FP1 is named in the same sentence as 2 diseases in open-access papers, as found by Europe PMC text mining. Sharing a sentence is not in itself a finding about the gene and the disease.
DISC1FP1 shares sentences with these, for which no sentence is quoted: schizoaffective disorder (1 paper); schizophrenia (1).